EGFR (epidermal growth factor receptor)
Diseases named in the same sentence as EGFR in open-access papers (continued):
Sharing a sentence is not in itself a finding about the gene and the disease.
cancer (continued). "Anti-EGFR therapy generally improves survival in EGFR-positive cancer patients." (PMID 28513565, 2017). "The relevance both EGFR and cancer cell malignancy has previously been reported." (PMID 29069815, 2017). "It will be interesting to analyze whether other β-HPVE6 proteins are able to bind the Y-phosphorylated EGFR and to stimulate the UV-dependent activation of the EGFR as well and whether this is linked to E6 proteins of HPV types that are cancer associated." (PMID 29176966, 2017). "Increased DNA-PKcs and epidermal growth factor receptor (EGFR) activities are positively correlated, and may contribute to metastatic phenotype and therapeutic resistance in human cancer cells." (PMID 28684677, 2017). "Thus, this evidence consolidates the importance of SCD1 in EGFR-mediatedlung cancer development and progression." (PMID 28724430, 2017). "In addition to understanding these signaling pathways in cancer, the spatial and temporal regulation of the EGFR remain understudied." (PMID 28513565, 2017). "EGFR was proposed as a target for cancer therapy nearly 30 years ago, and currently, monoclonal antibodies (mAbs) and tyrosine kinase inhibitors (TKIs) targeting EGFR are commercially available for cancer treatment." (PMID 29056908, 2017). "Nuclear EGFR is of huge potential interest in the diagnosis and treatment of cancer." (PMID 28646091, 2017). "The phosphoinositide 3-kinase/protein kinase B/mammalian target of rapamycin (PI3K/Akt/mTOR) pathway, which is downstream of EGFR signaling, may also play an important role in cancer." (PMID 27935858, 2017). "Triptolide could also be used in conjunction with EGFR TKIs as long-term therapy with these drugs was shown to enrich cancer stem cells." (PMID 28460475, 2017). "Our results suggest that VJ inhibited cancer cell growth and could be a potent molecule to inhibit EGFR and AKT signaling in NSCLC." (PMID 29234489, 2017). "The drug loaded Fab̕-TSL cytotoxicity was also correlated to EGFR density on the cancer cells." (PMID 29552041, 2017). "An EGFR kinase domain duplication has also been found in lung, brain, and other cancers." (PMID 28574446, 2017). "EGFR is a growth factor of great importance for prognosis and treatment in other types of cancer." (PMID 28489591, 2017). "Furthermore, the finding that the EGF neutralizing antibody prevented the hypoxia‐induced increase in viable cell numbers supports the notion that hypoxia‐induced EGF production serves as an autocrine loop to activate EGFR in cancers." (PMID 28330951, 2017). "EGFR can activate cancer cell motility and invasion by regulating CD44 and EMMPRIN." (PMID 28465354, 2017). "GE11 surface modification significantly enhanced the cellular uptake of Se NPs through EGFR-mediated endocytosis in EGFR over-expressed cancer cells, which resulted in enhanced inhibition effects against cancer cells and reduced toxicity against normal cells of GE11-Ori-Se NPs." (PMID 29019267, 2017). "Study has found that EGFR could be adjusted by EGF-meditated cancer cell proliferation through sialylation." (PMID 28978315, 2017). "In clinical practice, EGFR inhibitors had improved the prognosis of several cancers." (PMID 28352075, 2017). "EGFR is overexpressed in ∼50% of human cancers and is a target for cancer therapies." (PMID 28646091, 2017). "EGFR signaling is crucial in the regulation of cancer cell proliferation, migration and survival." (PMID 29069805, 2017). "It has been suggested that EGFR-driven intracellular signaling may control angiogenesis and pharmacological inhibition of EGFR reduces VEGF expression in cancer cells." (PMID 29270405, 2017). "These three truncated isoforms have different tissue expression patterns, are expressed in different cancers, and may play a role in supressing cell growth by inhibiting EGFR." (PMID 28846689, 2017). "Thus, we think that this novel strategy would be applied to treat cancer cells expressing higher level of the EGFR." (PMID 28887524, 2017).
cancer (continued). "Indeed, Haeri and co-workers designed thermosensitive liposomes functionalized with GE11 and Fab fragments of cetuximab in order to specifically and more efficiently bind EGFR-overexpressing cancer cells." (PMID 29271876, 2017). "Nevertheless, this newfound appreciation of the link between EGFR inhibitors and the immune system provides novel insights into how EGFR antagonists may function during cancer treatment, permiting adjustments to our current use of these drugs in the clinic." (PMID 28970798, 2017). "In addition, aspirin and its derivatives prevent cancer cell proliferation by reducing epidermal growth factor receptor (EGFR) expression and downstream signal transduction." (PMID 29246216, 2017). "Therefore, understanding of the regulation of EGFR expression is of great importance for cancer prevention and intervention." (PMID 28947780, 2017). "In this respect, although the clinical outcome of RAS/BRAF WT mCRC has been improved in recent years for the integration of EGFR agents in the continuum of care, the antitumor efficacy of these drugs is transient and EGFR inhibitor-acquired cancer resistance occurs." (PMID 29137301, 2017). "Consequently leading to consistent activation of second messenger signaling, PAR-1 cooperates with growth factor receptor (EGFR) and ErbB / Her2 or MMP-1 derived from fibroblasts to mediate Ca2+ pathway in cancer." (PMID 29291033, 2017). "Accordingly, high-EGFR expression is a common feature of multiple cancers." (PMID 29084952, 2017). "The altered expression of these markers may make cancer cells more amenable to EGFR-specific CAR-NK-92 cell-mediated killing." (PMID 29423418, 2017). "All together, these findings suggest that targeting cellular metabolism may become a new paradigm to improve the responses of cancer cells to both conventional and EGFR-targeted therapeutics for HNSCC." (PMID 27926487, 2017). "The co-expression of CD73 and EGFR has been reported in other types of cancers." (PMID 28158983, 2017). "Previous studies showed that EGFR signal is down regulated in quiescent cancer stem cells." (PMID 29108242, 2017). "Since EGFR is an important anti-cancer target that is overexpressed in multiple cancer cells and is also a direct target for SMFs, we hypothesized that it may played a key function in SMF-induced cell type and density-dependent cell proliferation inhibition." (PMID 28061454, 2017). "Moreover, NCTD-induced cell death was comparable to that of the anti-cancer drug gefitinib, a tyrosine kinase inhibitor for EGFR, based on the immunoblot analysis of the expressed proteins after the treatment of NCTD." (PMID 28086832, 2017). "For this reason, EGFR is an attractive target for anti-cancer therapy." (PMID 28978055, 2017). "Additionally, the growth factor receptors IGFR and EGFR, which cause PI3K-Akt-mTOR pathway activation and foment cancer cell proliferation were also downregulated upon TH588-treatment." (PMID 28542590, 2017). "The epidermal growth factor receptor (EGFR) is a glycoprotein involved in several human cancers." (PMID 28099906, 2017). "Small molecule EGFR inhibitors, such as erlotinib, gefitinib and lapatinib, compete specifically with ATP for bind to the catalytic tyrosine kinase domain, inhibiting autophosphorylation processes and downstream signaling of cancer cells." (PMID 28218686, 2017). "In comparison, exogenous protein targeting has allowed identification of several biomarkers which are overexpressed in many types of cancer such as the cell surface receptors EGFR and VEGFR which have been studied as targets for therapeutic drug delivery and diagnostic imaging." (PMID 27379987, 2017).
cancer (continued). "In addition, we also found that EGFR CNG in both female and male patients and CNG of HER3 and HER4 in male patients were closely associated with increased risk of cancer-related death." (PMID 29190914, 2017). "We have reported previously that in certain types of cancer cells, tTG expression can be up-regulated through EGFR-dependent signaling, and so we investigated whether there was an apparent difference in EGFR expression status between MES and PN GSCs." (PMID 28423611, 2017). "Particularly, EGFR and ErbB2 proteins hyperactivate theses pathways in a broad range of cancers." (PMID 28417948, 2017). "EGFR is often over-expressed or over-activated in human cancer." (PMID 28456787, 2017). "It has become increasingly clear that the plasticity of TNBCs with a mesenchymal stem-like phenotype is pivotal in malignant tumor progression and VM, and may also in part account for the resistance to EGFR TKIs18." (PMID 28425453, 2017). "SEMA3C-induced upregulation of EGFR could have profound implications in cancer development and could underpin our findings and those of studies involving semaphorins elsewhere." (PMID 28904399, 2017). "This interesting finding could be explained by the unique biology of each cancer type, where mutant EGFR/KRAS would strongly activate MAPK pathway in NSLSC." (PMID 28611673, 2017). "We hypothesize that the formation of the hydrogen bond might possibly permit the indacaterol molecule to be inserted into the binding cavity and therefore explain its specificity to EGFR T790M expressing cancer cells." (PMID 29238696, 2017). "In addition, fibroblasts (or recombinant HGF) promote survival of cancer cells and represent an important source of primary and acquired resistance to targeted therapy, including inhibitors of EGFR." (PMID 28420162, 2017). "EGFR was an oncogene overexpressed in several human cancers." (PMID 28460433, 2017). "Thus, combining the antioxidant CAT-SKL with the SMKI erlotinib targets both CSCs and bulk cancer cells in cultures of EGFR-expressing TNBC-derived cell lines." (PMID 28281569, 2017). "However, unbalanced ErbB activation in cancer can also result from defects in EGFR feedback regulation." (PMID 29229958, 2017). "Some other studies also demonstrated that miR-7 can regulate the occurrence of various cancers through repressing its target genes like EGFR (epidermal growth factor receptor), ACK1 (Activated Cdc42-associated Tyrosine Kinase 1), or IGF1R (insulin-like growth factor 1 receptor)." (PMID 28210621, 2017). "In the present study, we used different 2D and 3D cancer cell cultures and evaluated drug efficacies, oncoprotein addiction and cell survival in response to targeted drugs interfering with epidermal growth factor receptor (EGFR) signaling." (PMID 29296175, 2017). "Indeed, REP1 plays an important role in cancer progression, which is regulated by intracellular localization of EGFR or FOXO3." (PMID 28846638, 2017). "In addition, TMEM16A formed a complex with EGFR, and the complex regulated cancer proliferation in HNSCC cells." (PMID 28893247, 2017). "Thus, Mt4-mmp positively promotes cancer cell proliferation by enhancing the EGFR signaling pathway independently on the catalytic site of the enzyme." (PMID 28926609, 2017). "Notably, Annexin A2 interacts with EGFR at the cell surface and has an important role in cancer cell proliferation and migration by modulating EGFR functions." (PMID 28886730, 2017). "The first and most obvious is that patients with certain cancer types driven by EGFR signaling, which also have a high expression of oncomotif-miRNAs, may benefit from treatment with therapies targeting EGFR." (PMID 27477696, 2017). "As many tumors overexpress both EGFR and Src, it is reasonable to infer that inhibition of both targets may be beneficial for cancer therapy." (PMID 28086226, 2017). "Co-expression of CD73 and EGFR or VEGF has been found in other type of cancers." (PMID 28202050, 2017).
cancer (continued). "Therefore, drugs that target the EGFR signaling pathway have been approved for the treatment of cancer." (PMID 29018350, 2017). "EGFR is associated in epithelial cells with the heavily glycosylated transmembrane mucin protein MUC1, a natural ligand of galectin-3 that is overexpressed in cancer." (PMID 28731466, 2017). "It was also revealed that this loop had a major role in cancer types with high EGFR expression." (PMID 28957417, 2017). "Epidermal growth factor receptor (EGFR) is an important target for cancer therapy." (PMID 28630865, 2017). "Instead, EGFR expression after PDT is photosensitizer-dependent, whereby inhibition of EGFR by PDT may contribute to an anti-cancer effect when photosensitizers are employed that induce its downregulation, such as ZnPC, by an as yet undefined mechanism." (PMID 27803950, 2017). "Inhibition of ADAM family metalloproteases for modulating EGFR pathways may offer a potentially therapeutic strategy for human cancers." (PMID 28537886, 2017). "A number of different direct modes of action have been suggested that may explain the clinical efficacy of EGFR antagonist treatment in cancer therapy." (PMID 28970798, 2017). "This suggests the possibility that elevation of EGFR in different types of cancer may be partly due to the stabilization of the receptor through increased neddylation." (PMID 28891468, 2017). "The epidermal growth factor receptor (EGFR, also known as ErbB1), a 170-kDa transmembrane tyrosine kinase receptor, is a member of the receptor tyrosine kinases family and promotes cell proliferation, migration, and differentiation in variety of cancers." (PMID 29221140, 2017). "Furthermore, we examined the relative endogenous expression levels of miR-1 in cancer tissues with an up- or down-regulated EGFR signaling gene signature." (PMID 28537886, 2017). "However, on account of the development of drug-resistance, most anti-EGFR-targeted agents are unable to repress cancer progression." (PMID 28430586, 2017). "Our data collectively support a model in which MUC1 induces acquired chemotherapy resistance by upregulating ABCB1 in an EGFR-dependent manner, providing a novel molecular basis of using the EGFR inhibitor in MUC1-positive cancers to prevent chemotherapy resistance." (PMID 28796259, 2017). "The authors showed that pre-treatment of breast cancer cells with erlotinib, a targeted EGFR inhibitor, was required to sensitize cancer cells to doxorubicin and that co-administration of both (i.e., erlotinib and doxorubicin simultaneously) was not nearly as effective." (PMID 28887666, 2017). "In addition, NCTD-induced cell death was comparable to that of the anti-cancer drug gefitinib, a tyrosine kinase inhibitor for EGFR, based on the immunoblot analysis of the expressed proteins after the drug treatment." (PMID 28086832, 2017). "RHBDD1 is overexpressed in CRC, and EGFR is overexpressed in many cancers." (PMID 28445956, 2017). "Notably, AT1R transactivates EGFR in several cancers, leading to extracellular-regulated kinase (ERK) activation, phosphorylation of signal transducer and activator of transcription 3 (STAT3) and activation of protein kinase C (PKC)." (PMID 28052030, 2017). "Thus, HER3 appears to be a critical primary target for the development of cancer therapies, perhaps in conjunction with EGFR, HER2 and/or AKT targeting and/or chemotherapy." (PMID 28881753, 2017). "One of the popular explanations for this phenomenon is that the discordance of drug concentration of EGFR-TKIs between in cerebrospinal fluid and in serum, and the overall survival benefit of EGFR-TKIs provide chance and time for cancer cell colonization and proliferation in the brain, respectively." (PMID 28881820, 2017). "This strategy of exploiting a less-selective type II RTK binding profile may have merit in GBM, where EGFR is predominately amplified and has been shown to propagate cancer signalling in parallel to MET." (PMID 28696366, 2017).
cancer (continued). "However, EGFR has been shown in many cancer types to confer a survival advantage, that is to say it is pro‐proliferative and anti‐apoptotic." (PMID 28330951, 2017). "Since both patients were diagnosed with TNBC they were likely to experience early PD and death but the upregulation of EGFR expression in patient #8 after 6 months of chemotherapy clearly shows that cancer cells survive and continue to evolve during chemotherapy." (PMID 28489591, 2017). "For instance, mTORC2→NF-κB signaling is involved in cancer progression downstream of EGFR." (PMID 28492364, 2017). "Secondly, EGFR TKIs upregulate autophagy in many cancer cells." (PMID 28558758, 2017). "In cancer cells, integrin α6β4 signaling is activated upon binding to laminin extracellular matrix proteins and in cooperation with growth factor receptors such as EGFR, RON, and c-MET4–6." (PMID 28733611, 2017). "Therefore, additional research should be undertaken in order to identify the mechanisms involved and to provide better therapy strategies for the cancer-drugs and gene-target therapies "EGFR" clinically used in the treatment of NSCLC patients." (PMID 28904641, 2017). "The EGF-EGFR pathway plays an important role in cancer metastasis by activating the downstream PI3K/Akt, ERK and JNK pathway, the inhibition of EGFR or its downstream signal pathway will inhibit cancer metastasis, which sometimes will not reduce cell viability." (PMID 27906672, 2017). "We also suggest that this target-specificity of the EGF-GNP conjugates could aim cancer cells expressing high level of the EGFR such as breast cancer." (PMID 28887524, 2017). "EGFR inhibitors already constitute the first-line therapy for a number of cancers and our studies suggest another clinically significant indication where EGFR inhibitors may be of therapeutic benefit." (PMID 28374780, 2017). "Thus, the rationale for EGFR-targeted approaches to cancer treatment is apparent and now well-established." (PMID 28832537, 2017). "Moreover, we found that knockdown of expression of CLPTM1L, ATP9B, PQLC1 as well as EGFR significantly inhibited cancer cell migration and invasion." (PMID 28548104, 2017). "The cross talk between the EGFR and Notch pathways has been identified in several cancers including CRC, suggesting that possible combinations of MK0752 with cetuximab in these tumors might elicit antitumor response." (PMID 28473715, 2017). "Next, to explore the EGFR-downstream regulators involved in the cancer stemness property, we investigated whether SET domain-containing proteins, which can methylate on H3K9, were associated with maintaining this property." (PMID 28787001, 2017). "EGFR (in KEGG, Reactome, and WikiPathway) and ErbB2 (in Reactome) are reported to be frequently mutated and/or over-expressed in various types of cancer resulting in aberrant activities contributing to abnormal cell growth, survival, migration, and differentiation." (PMID 28288164, 2017). "Hence, EGFR-targeted therapy is a promising approach for cancer treatment and significant efficacy of anti-EGFR antibody, such as cetuximab, has been shown in HNSCC." (PMID 28038457, 2017). "Changes in the cell population embody the characteristic of cancer plasticity, which could explain how genetic alterations contribute to EGFR or ALK resistance." (PMID 27757846, 2017). "It has been shown that cancer vaccines reprogram the immune response to prevent, reject, and detect premalignant cells, which might be applicable in EGFR therapy." (PMID 28430586, 2017).